ANXA2 (annexin A2)
Diseases named in the same sentence as ANXA2 in open-access papers (continued):
Sharing a sentence is not in itself a finding about the gene and the disease.
kidney diseases (6 papers, 2016 to 2025). "ANXA2 antibody, gene silencing techniques and ANXA2 protein administration have been used in cellular and animal experiments to explore the role of ANXA2 in kidney diseases, as well as the underlying mechanisms." (PMID 36120574, 2022). "Of note, the current knowledge regarding the role of ANXA2 in kidney diseases is very limited, and many of the publications are association studies." (PMID 36120574, 2022). "Recent studies implicated that ANXA2 is an important participant in the pathogenesis of various kidney diseases." (PMID 36120574, 2022). "Thus, annexin A2 is implicated in the pathogenesis and progression of various kidney diseases." (PMID 36120574, 2022). "Using existing datasets, we analyzed transcription of AnxA2 in three different mouse models of lupus-like kidney disease." (PMID 40889685, 2025). "A continuous increase in Anxa2 level promotes inflammatory responses and initiates damage binding to auto-antibodies in renal diseases." (PMID 37955107, 2023). "Further studies are needed to determine its function and develop effective therapeutic methods to treat renal diseases by directly targeting Anxa2." (PMID 37955107, 2023). "Annexin A2 executes multiple cellular process and signaling pathways to participate in the pathogenesis and progression of various kidney diseases." (PMID 36120574, 2022). "Given the pathogenic role that the alternative pathway plays in different kidney diseases, therapies that reverse these effects of AnxA2 may protect the kidney from complement-mediated injury." (PMID 40889685, 2025). "Finally, using preclinical and clinical datasets, we examined the expression of AnxA2 in several kidney diseases." (PMID 40889685, 2025). "There is a growing body of evidence focused on Anxa2 in renal diseases." (PMID 37955107, 2023). "Therefore, future more definitive and mechanistic studies on the role of ANXA2 in the pathogenesis of kidney diseases are warranted." (PMID 36120574, 2022). "In this review, we focus on the current understanding of the role of annexin A2 in kidney diseases." (PMID 36120574, 2022). "Aberrant expression of annexin A2 has been found in numerous kidney diseases." (PMID 36120574, 2022). "However, the function of Anxa2 in different kidney diseases is varied and intricate." (PMID 37955107, 2023).
adenocarcinoma (5 papers, 2014 to 2021). A common cancer characterized by the presence of malignant glandular cells. "In mouse adenocarcinoma models, knockdown of ANXA2 significantly inhibited cell metastasis." (PMID 33658625, 2021).
infectious disease (2 papers, 2023). A disorder directly resulting from the presence and activity of a microbial, viral, or parasitic agent in humans. "Collectively, our findings broaden our understanding of the molecular mechanisms of ANXA2 in alphaherpesvirus pathogenicity and suggest that ANXA2 is a potential therapeutic target for treating alphaherpesvirus-induced infectious diseases." (PMID 36786600, 2023). "Thus, targeting Annexin A2 may present a promising therapeutic approach for the treatment of diverse infectious diseases." (PMID 37482693, 2023).
inflammation (2 papers, 2017 to 2021). Aberrant reaction of the microcirculation characterized by movement of fluid and leukocytes from the blood into extravascular tissues. "Strikingly, these toxic side effects can be overcome by an AnxA2 peptide inhibitor (TM601) or AnxA2 deficiency in mice, alleviating bleomycin-induced pulmonary inflammation and fibrosis." (PMID 33810523, 2021).
retinopathy (2 papers, 2009 to 2016). "Studies performed with whole retinal sample collections describe a contribution of Anxa2 and Anxa3 in neovascularization neonatal models of oxygen-induced retinopathy where they were significantly up-regulated." (PMID 26324419, 2016). "Annexin A2 mRNA expression was investigated in the mouse model of hypoxia-induced retinopathy." (PMID 19536308, 2009). "At P15, mice that had been reared in room air had normal retinas and no detectable staining for annexin A2, yet retinopathy showed prominent staining that colocalized with CD31, which selectively stains endothelial cells." (PMID 19536308, 2009).
heart disease (1 paper, 2024). "ANXA2 also interacts with CXCL12 (SDF1), a BMP9-inducible protein in endothelial cells and a well-defined homing molecule identified for improved stem cell treatments in heart disease." (PMID 39430425, 2024).
ANXA2 also shares sentences with these, for which no sentence is quoted: pneumonia (5 papers); nonalcoholic fatty liver disease (4); acute pancreatitis (3); neurodegenerative disease (3); osteoarthritis (3); Arthritis (2); asthma (2); atypical endometrial hyperplasia (2); bacteremia (2); cervical squamous cell carcinoma (2); chronic obstructive pulmonary disease (2); colonic adenocarcinoma (2); colorectal adenocarcinoma (2); dyslipidemia (2); fibrosarcoma (2); fibrosis (2); hemorrhage (2); Hypertension (2); idiopathic pulmonary fibrosis (2); inflammatory myopathies (2); influenza (2); intracerebral hemorrhage (2); kidney (2); lung squamous cell carcinoma (2); multiple sclerosis (2); nephrolithiasis (2); Nephropathy (2); primary Sjögren's syndrome (2); sarcoma (2); systemic sclerosis (2).
A further 92 diseases each share a sentence with ANXA2 in 2 papers or fewer.